BCR (BCR activator of RhoGEF and GTPase)
Diseases named in the same sentence as BCR in open-access papers (continued):
Sharing a sentence is not in itself a finding about the gene and the disease.
kidney disease (1 paper, 2024). "B-cells from hybrid controls and kidney disease patients at all time points segregated into four dominant regions based on BCR isotype." (PMID 38806532, 2024).
BCR also shares sentences with these, for which no sentence is quoted: B-cell acute lymphoblastic leukemia (9 papers); chronic myelomonocytic leukemia (6); common variable immunodeficiency (4); mixed phenotype acute leukemia (4); ovarian carcinoma (4); anaplastic large cell lymphoma (3); Ataxia-telangiectasia (3); heart failure (3); Hepatosplenomegaly (3); rheumatoid arthritis (3); T-lymphoblastic lymphoma (3); acute megakaryoblastic leukemia (2); anemia (2); bacterial infection (2); breast tumors (2); diabetes (2); juvenile myelomonocytic leukemia (2); marginal zone lymphoma (2); pneumonia (2); pulmonary hypertension (2); acute GVHD (1); Acute hepatitis (1); acute respiratory distress syndrome (1); adenocarcinoma (1); Adrenocortical Carcinoma (1); Allergy (1); blast crisis (1); bone marrow failure (1); brain trauma (1); breast adenocarcinoma (1).
A further 63 diseases each share a sentence with BCR in 1 paper.